HPCA (hippocalcin)
Description:
Calcium-binding protein that may play a role in the regulation of voltage-dependent calcium channels. May also play a role in cyclic-nucleotide-mediated signaling through the regulation of adenylate and guanylate cyclases (By similarity).
Synonyms: BDR2; DYT2
Tractability: Small molecule: a structure with a bound ligand is known. Antibody: UniProt places it where antibodies can reach, with medium confidence. PROTAC: ubiquitination databases record sites on it; its protein half-life has been measured.
Gene: Protein-coding gene on chromosome 1 (32,881,498 to 32,898,441, forward strand). Ensembl gene ENSG00000121905.
Subcellular location: Cytoplasm, cytosol; Membrane
Gene Ontology:
Molecular function: actin binding; calcium ion binding; identical protein binding; protein binding; kinase binding
Biological process: cellular response to calcium ion; regulation of voltage-gated calcium channel activity; regulation of signal transduction; calcium-mediated signaling; cellular response to electrical stimulus; cellular response to L-glutamate; positive regulation of protein targeting to membrane; regulation of postsynaptic neurotransmitter receptor internalization; response to Aroclor 1254; response to ketamine; response to L-glutamate; retina development in camera-type eye
Cellular component: cytoplasm; cytosol; membrane; axon; dendrite cytoplasm; dendrite membrane; dendritic spine head; glutamatergic synapse; neuronal cell body membrane; perikaryon; postsynapse
Genetic constraint (gnomAD): Loss-of-function variants: 4 observed, 16.44 expected, observed/expected ratio (o/e) 0.24, 90% interval 0.12 to 0.56. The upper end of that interval is the gene's LOEUF score, 0.56, which puts it in group 2 of 6, group 1 being the genes least tolerant of losing a copy. Missense variants: 161 observed, 261.19 expected, observed/expected ratio (o/e) 0.62, 90% interval 0.54 to 0.7. Synonymous variants: 93 observed, 98.98 expected, observed/expected ratio (o/e) 0.94, 90% interval 0.79 to 1.12.
Gene-disease validity (ClinGen):
ClinGen rates the evidence that HPCA causes each of these diseases.
complex movement disorder with or without neurodevelopmental features (autosomal recessive): Definitive. A movement disorder characterized by having one or more different types of movement disorders, such as abnormal muscle tone, abnormal degree of movement, dystonia or torsion, which may occur with or without neurodevelopmental features, such as developmental delay or intellectual disability.
Homologues: Orthologues: chimpanzee HPCA (100% identical), dog HPCA (100% identical), guinea pig HPCA (100% identical), macaque HPCA (100% identical), mouse Hpca (100% identical), pig HPCA (100% identical), rabbit HPCA (100% identical), rat Hpca (100% identical), zebrafish hpca (94% identical), tropical clawed frog hpca (91% identical), Caenorhabditis elegans ncs-2 (48% identical), Drosophila melanogaster CG7646 (44% identical). Paralogues in human: HPCAL1 (94% identical), NCALD (88% identical), HPCAL4 (67% identical), VSNL1 (66% identical), NCS1 (57% identical), RCVRN (51% identical), GUCA1B (44% identical), KCNIP2 (43% identical), KCNIP1 (41% identical), KCNIP3 (40% identical), KCNIP4 (40% identical), GUCA1A (38% identical), and 2 more.
Diseases named in the same sentence as HPCA in open-access papers:
HPCA is named in the same sentence as 20 diseases in open-access papers, as found by Europe PMC text mining. Sharing a sentence is not in itself a finding about the gene and the disease. The quoted sentences say what the papers report.
Dystonia (14 papers, 2013 to 2025). An abnormally increased muscular tone that causes fixed abnormal postures. "Like ANO3 variants, mutations in hippocalcin were shown to contribute to the appearance of dystonia." (PMID 39773217, 2025). "The highest rates of the variants have been found in the PRKRA and HPCA genes in our dystonia cohort." (PMID 38458754, 2024). "In humans, rare missense and null mutations in HPCA have been linked to DYT2 primary isolated dystonia, a hyperkinetic movement disorder affecting the upper limbs, cervical and cranial regions." (PMID 30865587, 2019). "Two other recessively inherited isolated dystonias have also been described arising from mutation of DYT2 (HPCA) or DYT27 (COL6A3)." (PMID 29110692, 2017). "Our data demonstrate that the dystonia-causing mutations strongly affect hippocalcin cellular functions which suggest a central role for perturbed calcium signalling in DYT2 dystonia." (PMID 28398555, 2017). "Using a combination of biochemical and biophysical techniques, we demonstrated the calcium-dependent oligomerisation of hippocalcin and a strong defect in oligomer formation for the dystonia-causing mutants." (PMID 28398555, 2017). "In summary, we have presented evidence to support biallelic mutations in HPCA as a cause of AR primary isolated dystonia." (PMID 25799108, 2015). "Subsequently, compound-heterozygous mutations in HPCA were also identified in a second independent kindred affected by AR isolated dystonia." (PMID 25799108, 2015). "HPCA deficiency was initially associated to isolated dystonia, but subsequent reports expanded the clinical phenotype, describing patients presenting with variable combinations of seizures, developmental delay, intellectual disability, psychiatric symptoms, and dysphagia." (PMID 36003298, 2022). "For the dystonia-causing mutants hippocalcin(T71N) and hippocalcin(A190T), calcium influx upon stimulation significantly increased to 51% and 62%, respectively, compared to hippocalcin wild-type." (PMID 28398555, 2017). "In this paper, we investigated the role of mutations in hippocalcin, a neuronal calcium sensor involved in DYT2 dystonia disease." (PMID 28398555, 2017). "This identification of variants in hippocalcin, an NCS protein detected in greatest abundance in the striatum, as the cause of a Mendelian form of dystonia suggests a role for perturbed calcium signaling in the pathogenesis of this condition." (PMID 25799108, 2015). "In addition to these 45 individuals, we identified ten carriers of single heterozygous pathogenic variants in recessively inherited dystonia genes, including AOPEP (n=5), SPR (n=4), and HPCA (n=1)." (PMID 40672488, 2025). "The identification of mutations in HPCA as a cause of AR primary isolated dystonia paves the way for further studies to assess whether “DYT2 dystonia” is a genetically homogeneous condition or not." (PMID 25799108, 2015). "Of note, for several established dystonia genes, no carrier of a disease‐causing variant was identified in our large patient group (e.g., in AOPEP, HPCA, PRKRA, and TH)." (PMID 40533913, 2025). "Importantly, the phenotypes associated with mutations in the DYT genes enriched in the putamen ‘cyan’ module belonged to different clinical subtypes of dystonia, namely isolated dystonia (ANO3 and HPCA), combined dystonia (KCTD17 and ADCY5), and paroxysmal dystonia (KCNA1, CACNA1A, PRRT2 and SCN8A)." (PMID 32889528, 2020).
Cerebral ischemia (2 papers, 2024). Restriction of arterial blood supply to the brain associated with insufficient oxygenation to support the metabolic requirements of the tissue. "This suggests that the function of Tat-HPCA as a calcium sensor protein contributed to the protective effect against cerebral ischemia." (PMID 38192804, 2024). "Thus, we demonstrate that EGCG exerts a neuroprotective effect by regulating hippocalcin in cerebral ischemia." (PMID 38427657, 2024).
Huntington disease (2 papers, 2018 to 2022). Huntington disease (HD) is a rare neurodegenerative disorder of the central nervous system characterized by unwanted choreatic movements, behavioral and psychiatric disturbances and dementia. "Finally, decreased DREAM mRNA and protein levels and hippocalcin mRNA expression were found in striatum from Huntington’s disease patients." (PMID 29523177, 2018).
Anxiety (1 paper, 2024). Intense feelings of nervousness, tension, or panic often arise in response to interpersonal stresses. "The correlation between anxiety and decreased hippocalcin myelin protein expression in the amygdala might reflect the role of hippocalcin in neuronal excitability as a diffusible calcium sensor." (PMID 39684893, 2024).
breast carcinoma (1 paper, 2024). "Based on our extensive search, it also identified several new potential genes associated with breast cancer progression, including HPCA, SLC9A2, SCNN1B, SULT4A1, and GUCY2D." (PMID 39768011, 2024).
developmental delay (1 paper, 2022). "Global developmental delay and subsequent moderate to severe intellectual disability are observed in almost all patients with GNB1, GNAO1, PDE2A, and HPCA variants." (PMID 36003298, 2022).
Encephalopathy (1 paper, 2022). Encephalopathy is a term that means brain disease, damage, or malfunction. "Epilepsy can be prominent in GNB1 and GNAO1 encephalopathy, while it is anecdotical in individuals with HPCA, PDE2A, and PDE10A pathogenic variants." (PMID 36003298, 2022).
epilepsy (1 paper, 2022). A brain disorder characterized by episodes of abnormally increased neuronal discharge resulting in transient episodes of sensory or motor neurological dysfunction, or psychic dysfunction. "While the clinical phenotype associated with ADCY5 and GNAL is characterized by movement disorder in the absence of epilepsy, GNAO1, GNB1, PDE2A, PDE10A, and HPCA have a broader clinical phenotype, encompassing movement disorder, epilepsy, and neurodevelopmental disorders." (PMID 36003298, 2022).
ischemic stroke (1 paper, 2024). A stroke disorder caused by obstruction of blood flow to the brain, due to thrombotic (local blood clot formation) or embolic (due to a blood clot or other material traveling from another site) event. "This study focused on the expression of hippocalcin protein by EGCG in animal models of ischemic stroke." (PMID 38427657, 2024). "We hypothesized that EGCG administration may affect changes in hippocalcin in ischemic stroke." (PMID 38427657, 2024). "Thus, we investigated whether EGCG has a neuroprotective effect through the regulation of intracellular calcium concentration and hippocalcin expression in animal model of ischemic stroke and glutamate-exposed cells." (PMID 38427657, 2024).
Stroke (1 paper, 2024). Sudden impairment of blood flow to a part of the brain due to occlusion or rupture of an artery to the brain. "We investigated whether EGCG treatment regulates the expression of hippocalcin in stroke animal model and glutamate-induced neuronal damage." (PMID 38427657, 2024).
HPCA also shares sentences with these, for which no sentence is quoted: Autoimmunity (1 paper); glioma (1); Intellectual disability (1); movement disorder (1); neurodevelopmental disorder (1); ocular toxoplasmosis (1); paroxysmal dystonia (1); Primary Torsion Dystonias (1); psychosis (1); tumor (1).